CRP (C-reactive protein)
Diseases named in the same sentence as CRP in open-access papers (continued):
Sharing a sentence is not in itself a finding about the gene and the disease.
leukocytosis (continued). "At this point, SARS-CoV-2 remained detectable through the multiplex respiratory panel, and inflammatory markers were elevated, with a C-reactive protein of 21.13 mg/dL, procalcitonin of 0.69 ng/mL, and leukocytosis of 11.7 × 109/L with neutrophilia (10.51 × 109/L)." (PMID 41480435, 2025). "Labs showed leukocytosis, elevated CRP, and pre-renal azotemia." (PMID 40961887, 2025). "Laboratory results showed mild anemia (6.1 mmol/L), thrombocytosis (570x109 cells/L), leukocytosis (34.1x109 cells/L with neutrophil dominance (23.9x109 cells/L), C-reactive protein (CRP) (170 mg/L), hyperbilirubinemia (98 μmol/L), increased creatinine (117 μmol/L) and alanine transaminase (95 U/L)." (PMID 41550931, 2025). "Additionally, including CRP alongside leukocytosis and neutrophilia provides a more robust and quantifiable marker of inflammation." (PMID 41473919, 2025). "Initial laboratory evaluation demonstrated leukocytosis (white blood cell count 14,100/μL) and markedly elevated C-reactive protein (14.54 mg/dL), along with a profoundly elevated serum ammonia level of 380 μg/dL (reference 12-66 μg/dL) despite preserved hepatic function." (PMID 41458852, 2025). "Laboratory investigations revealed normal hemoglobin (12.6 g/dL) and hematocrit (38.4%), leukocytosis with elevated white blood cell count (13,200/μL), marked neutrophilia (polymorphonuclear predominance 82.3%), and a raised C-reactive protein (CRP) level of 8.8 mg/L." (PMID 40951094, 2025). "However, fever, leukocytosis, elevated CRP, ESR, procalcitonin, and ALP, along with decreased albumin, were significantly associated with pathogen isolation." (PMID 41010981, 2025). "Laboratory findings may reveal leukocytosis, elevated C-reactive protein (CRP), and increased erythrocyte sedimentation rate (ESR), all indicative of systemic inflammation." (PMID 40507733, 2025). "Mild leukocytosis and elevated CRP levels were initially observed." (PMID 40104470, 2025). "While not specific, laboratory findings such as elevated inflammatory markers (e.g., C-reactive protein) and leukocytosis may support the diagnosis of IPA." (PMID 41515529, 2025). "Laboratory investigations show leukocytosis and C-reactive protein levels > 20 mg/L." (PMID 40111719, 2025). "Laboratory tests revealed leukocytosis and elevated C-reactive protein levels." (PMID 40831843, 2025). "A retrospective study on 16 dogs diagnosed with bacterial discospondylitis showed that CRP assessment might be clinically more useful to screen this disease than pyrexia or leukocytosis alone." (PMID 40270003, 2025). "Leukocytosis and elevated C-reactive protein indicated systemic inflammation." (PMID 40922879, 2025). "However, distinguishing viral etiology from GAS pharyngitis is challenging even in the presence of tonsil exudates, high C-reactive protein, and leukocytosis." (PMID 40142520, 2025). "Laboratory data obtained on the day of admission showed marked leukocytosis, elevated C-reactive protein and D-dimer levels, and severe hyperammonemia, whereas liver enzymes and bilirubin were within or close to the normal ranges, indicating the absence of overt hepatic dysfunction." (PMID 41458852, 2025). "Laboratory results were relevant for leukocytosis and mild C-reactive protein (CRP) elevation." (PMID 40895668, 2025). "Analytically, leukocytosis, neutrophilia, high CRP, and high ESR were observed." (PMID 40161166, 2025). "At this point, owing to the clinical and imaging findings (positive Morphy's sign, leukocytosis, elevated CRP, thickened-walled vesicles, and hydrocholecyst), the Tokyo criteria for cholecystitis were met, which constituted an extremely atypical presentation of Mirizzi syndrome." (PMID 40026964, 2025). "Blood tests showed leukocytosis with neutrophilic predominance (56.4%) and elevated levels of C-reactive protein (CRP; 90 mg/L), serum amyloid A (SAA, 81.99 mg/L), erythrocyte sedimentation rate (48 mm/h), procalcitonin (1.65 ng/mL), and platelet count (442 × 109/L)." (PMID 40852416, 2025).
leukocytosis (continued). "Blood tests showed leukocytosis at 13,000/mm3 (normal range: 4,000-11,000/mm3), predominantly neutrophilic (9,000/mm3; normal range: 2,000-7,500/mm3), and an elevated C-reactive protein (CRP) level at 95 mg/L (normal value: <5 mg/L)." (PMID 41458702, 2025). "Initial laboratory tests revealed mild anemia (hemoglobin 104 g/L, mean corpuscular volume 96 fL), leukocytosis (white blood cell count 14.03 × 109/L with neutrophils 53.6%, lymphocytes 39.3%), thrombocytosis (platelet count 419 × 109/L), and elevated C-reactive protein (CRP 30.7 mg/L)." (PMID 41394827, 2025). "Laboratory data showed leukocytosis 17,000 cells/μL with neutrophilia, mild normochromic normocytic anemia with hemoglobin 11.2 g/dL, marked inflammatory syndrome with elevated C-reactive protein (CRP) of 180 mg/L, and an erythrocyte sedimentation rate (ESR) of 87 mm/h." (PMID 40729243, 2025). "Blood investigations showed anemia of 7.6 g/dL, hypoalbuminemia of 11 g/L, urine protein/creatinine ratio of 13.7 g/g, hyponatremia of 129 mmol/L, leukocytosis (leukocytes at 29,000/mm3), thrombocytosis of 798,000/mm3, and increased C-reactive protein (CRP) of 209 mg/L." (PMID 40070415, 2025). "These conditions may account for the patient’s rapid clinical decline despite appropriate antimicrobial therapy and are supported by rising inflammatory markers such as leukocytosis and elevated C-reactive protein levels." (PMID 40407649, 2025). "Laboratory testing revealed leukocytosis with a left shift, elevated C-reactive protein (CRP), and mild increases in lactate dehydrogenase (LDH) and creatine phosphokinase (CPK), while angiotensin-converting enzyme (ACE) and soluble interleukin-2 receptor (sIL-2R) levels were within normal limits." (PMID 41170255, 2025). "Common findings include leukocytosis, elevated CRP and/or ESR, and increased thyroglobulin levels." (PMID 40364264, 2025). "The laboratory tests revealed leukocytosis with granulocytosis, lymphopenia, and thrombocytopenia with extremely elevated inflammatory markers—CRP 503.2 mg/L, ferritin 8494.2 ng/mL, hypoalbuminemia, and elevated liver enzymes, elevated D-dimer ≥ 5× upper limit of normal." (PMID 40699733, 2025). "Complete blood count showed leukocytosis, piastrinosis, elevated CRP, and elevated procalcitonin." (PMID 40265142, 2025). "Given the restricted predictive ability of inflammatory markers including leukocytosis, CRP, and PCT for mortality, certain studies have explored other measurable laboratory markers associated with prognosis in CAP patients treated with prolonged glucocorticoids." (PMID 41158450, 2025). "The authors also observed leukocytosis and increased CRP, which may be attributed to the PG pro-inflammatory status, the frequent association with secondary infection, and peripheral neutrophilia induced by systemic corticosteroids." (PMID 40251072, 2025). "Laboratory findings showed leukocytosis and a C-reactive protein (CRP) of 373 mg/L." (PMID 41316033, 2025). "Laboratory tests revealed anemia with hemoglobin of 95 g/L (reference: 130-170 g/L), leukocytosis of 14.2 × 109/L (reference: 4.0-9.0 × 109/L), elevated erythrocyte sedimentation rate of 45 mm/h (reference: <15 mm/h), and C-reactive protein of 68 mg/L (reference: <5 mg/L)." (PMID 41210013, 2025). "Furthermore, complete blood count analyses in patients with HLH commonly reveal leukocytosis, anemia, thrombocytopenia, and elevated inflammatory markers such as C-reactive protein (CRP) and erythrocyte sedimentation rate (ESR)." (PMID 41020231, 2025). "The haematological profile we documented—marked leukocytosis without parallel CRP elevation—extends earlier work on measles-associated immune dysregulation." (PMID 40872832, 2025).
leukocytosis (continued). "Laboratory investigations revealed elevated myocardial enzymes, mild renal impairment (eGFR = 55 mL/min/1.73 m2), and systemic inflammatory markers, including leukocytosis (13,620/mm3) with eosinophilia (9.5%), elevated C-reactive protein (CRP = 17.5 mg/L), and IgE levels (180 UI/mL)." (PMID 39941439, 2025). "In our case, elevated C-reactive protein and leukocytosis were present." (PMID 40951031, 2025). "Blood tests showed mild leukocytosis and elevated C-reactive protein (CRP) levels." (PMID 40656252, 2025). "Labs revealed leukocytosis (17,000/mm3), CRP 175 mg/L, and renal insufficiency." (PMID 40961887, 2025). "Clinical indicators suggestive of bowel ischemia or perforation may include abdominal pain, localized tenderness or guarding, signs of systemic infection such as fever, elevated C-reactive protein levels, and leukocytosis." (PMID 40765586, 2025). "Thus, the markedly raised CRP and leukocytosis in this patient not only signify acute infection but also serve as surrogate indicators of severe pneumonia, consistent with the patient’s clinical and radiological findings." (PMID 41328147, 2025). "Similarly, no statistical associations were found between the CMV tissue density and levels of CRP, leukocytosis, albumin levels, or platelet count." (PMID 40725516, 2025). "Additionally, the most frequently observed physical examination and laboratory findings included rebound tenderness (24.6%), fever (15.6%), leukocytosis (25.4%), and elevated CRP levels (16.4%)." (PMID 40136596, 2025). "Laboratory tests showed leukocytosis (white blood cell count of 13.8 × 10^9/L with neutrophil predominance; reference range: 4.2 - 10.3 × 109/L) and an elevated C-reactive protein (CRP) of 137 mg/L (upper limit <10 mg/L), suggesting an active inflammatory process." (PMID 40062171, 2025). "Laboratory assessment revealed worsening leukocytosis and increasing levels of CRP." (PMID 40895668, 2025). "Blood tests revealed a mild leukocytosis and normal C-reactive protein (CRP)." (PMID 41220483, 2025). "The blood workup showed leukocytosis and high C-reactive protein levels." (PMID 40218164, 2025). "Moreover, clinical features such as anorexia, nausea or vomiting, leukocytosis, neutrophilia, and elevated CRP levels were significantly more common in children with appendicitis." (PMID 41473919, 2025). "Blood tests revealed leukocytosis and an elevated C-reactive protein." (PMID 40012964, 2025). "Laboratory results revealed leukocytosis, neutrophilia, and elevated C-reactive protein (CRP)." (PMID 40276424, 2025). "Blood tests showed leukocytosis at 21,360/mm3 and a CRP level of 10.7 mg/L." (PMID 40364883, 2025). "Factors such as the type of diarrhea, associated symptoms (e.g., abdominal pain, bloody stools), altered laboratory values (e.g., leukocytosis, elevated CRP), presence of comorbidities, and immunological status were analyzed to guide appropriate test utilization." (PMID 40426983, 2025). "Laboratory studies showed mild leukocytosis (8,550 cells/μL, CRP 1.18 mg/dL)." (PMID 41552223, 2025). "Follow-up laboratory findings showed leukocytosis at 28,200/mm3 and a CRP level of 350 mg/L." (PMID 40364883, 2025). "Laboratory investigations on admission revealed leukocytosis (white blood cell count 10,900/μL with 86% neutrophils), significantly elevated C-reactive protein (CRP) at 20.4 mg/dL (reference range <0.5 mg/dL), and procalcitonin (PCT) at 0.8 ng/mL (reference range <0.5 ng/mL)." (PMID 41497940, 2025). "It is commonly manifested through hyperfibrinogenemia, hypoalbuminemia, leukocytosis with a shift in leukocyte lineages and elevated C-reactive protein (CRP) levels, accompanied by metabolic alterations such as changes in body mass index (BMI) and hemoglobin concentration." (PMID 41302152, 2025). "Laboratory tests showed leukocytosis with neutropenia, CRP 80 mg/l, ferritin 1500 μg/l." (PMID 40374837, 2025).
leukocytosis (continued). "GIS involvement was significantly associated with leukocytosis (p < 0.001) and elevated C-reactive protein (CRP) (p = 0.018), but these parameters did not correlate with renal involvement." (PMID 40310537, 2025). "The blood test indicated the presence of an inflammatory syndrome, as evidenced by elevated levels of C-reactive protein (CRP) of 107 mg/L (normal range: <3 mg/L) and an increased white blood cell count (leukocytosis) of 13,000 × 106/L (normal count: 4,000-11,000 × 106/L)." (PMID 41244313, 2025). "Blood tests revealed leukocytosis, thrombocytopenia, and elevated liver enzymes and CRP." (PMID 41246602, 2025). "Repeat laboratory investigations showed persistent leukocytosis and elevated CRP, while other parameters - including blood urea nitrogen, creatinine, liver enzymes, lactate dehydrogenase, erythrocyte sedimentation rate, and procalcitonin - remained within normal limits." (PMID 40851708, 2025). "At the age of 22 years, at 28 weeks of pregnancy, P1 was hospitalized for septic shock, presenting with leukocytosis (25.7 × 109 cells per litre) with neutrophilia (18.80 × 109 cells per litre), high C-reactive protein concentration (CRP; 8.7 mg dl−1) and persistent fever (>38 °C)." (PMID 39198650, 2024). "Finally, this study found that leukocytosis, high NLR, high CRP, and high PCT are all associated with 30-day mortality." (PMID 38792539, 2024). "Laboratory findings indicated leukocytosis (22.15 × 109/L), normal hemoglobin level (118 g/L), thrombocytosis (688 × 109/L), elevated CRP level (117.7 mg/L), elevated erythrocyte sedimentation rate (49 mm/h), elevated procalcitonin (1.01 ng/mL), and decreased sodium concentration (132 mmol/L)." (PMID 39151496, 2024). "A peripheral blood examination revealed leukocytosis and elevated C-reactive protein levels." (PMID 39376867, 2024). "Investigation revealed a slight elevation of C-reactive protein and leukocytosis with neutrophilia." (PMID 39092363, 2024). "The highest body temperature and the severity of leukocytosis or C-reactive protein levels were not linked to poor outcomes." (PMID 38528535, 2024). "Laboratory evaluation was remarkable for leukocytosis to 12,440 cells/μL (reference range 4.50-13.00 103/μL) with neutrophil predominance of 9,600 cells/μL (reference range 1.80-8.00 103/μL), and elevated CRP to 13.4 mg/dL (reference range <0.5 mg/dL)." (PMID 39634689, 2024). "In addition, abdominal distension caused by CVB infectious-toxic enteroplegia, and respiratory catarrhal symptoms were present in our case, along with transient leukocytosis, initial thrombocytopenia, and consistently normal hypersensitive C-reactive protein." (PMID 38836060, 2024). "The exams indicate leukocytosis, severe anemia, and high CRP." (PMID 39135818, 2024). "Laboratory tests showed leukocytosis (17,300/μL) with neutrophilia (15,250/μL), and marked indications of inflammatory syndrome (CRP 244 mg/L, procalcitonin 7 ng/mL, ESR 70 mm/h, LDH 630 U/L, fibrinogen 961 mg/dL) with no hypoxemia on arterial blood gas analysis." (PMID 39768711, 2024). "However, laboratory findings, including significant leukocytosis with elevated neutrophil counts and CRP, along with a dramatic response to corticosteroids, supported the diagnosis of SSS." (PMID 39310601, 2024). "Spearman’s correlation analysis revealed a positive correlation of LOS with NLR (r = + 0.291, p = 0.041), leukocytosis (r = + 0.284, p = 0.045), neutrophilia (r = + 0.302, p = 0.033), CRP levels (r = + 0.426, p = 0.003), and heart rate (r = + 0.311, p = 0.028)." (PMID 38539204, 2024). "Elevated CRP and leukocytosis often shorten the time to diagnosis in patients with back pain." (PMID 39061353, 2024). "Other unfavorable prognostic factors are thoroughly described, including advanced age, male gender, as well as systemic inflammation markers such as elevated levels of C-reactive protein or lactate dehydrogenase, anemia, thrombocytosis, leukocytosis, or an increased neutrophil/lymphocyte ratio." (PMID 39629295, 2024).
leukocytosis (continued). "Blood analysis showed leukocytosis and elevated C-reactive protein." (PMID 38533169, 2024). "Additionally, common lab factors were identified as prognostically significant in one or more studies, including lactate dehydrogenase, WBC (leukocytosis), hemoglobin (anemia), and C-reactive protein levels." (PMID 38730606, 2024). "Laboratory investigation showed leukocytosis and high C-reactive protein." (PMID 38333502, 2024). "Leukocytosis, elevation of CRP, and metabolic acidosis as evidenced by the arterial blood gases combined with the radiological investigations provide an appropriate estimation of the patient's condition and early recognition and initiation of treatment, which can lead to a better prognosis." (PMID 39624520, 2024). "Other laboratory parameters indicated elevated C-reactive protein (CRP) levels and leukocytosis." (PMID 38975398, 2024). "Results of routine tests are usually non-specific, however, in GPA, as in other inflammatory diseases, patients usually have leukocytosis with increased neutrophilia, normocytic normochromic anemia (as an expression of inflammation), thrombocytosis and increased CRP or ESR." (PMID 39257888, 2024). "Laboratory tests revealed leukocytosis and elevated C-reactive protein (CRP) levels." (PMID 38500926, 2024). "Laboratory tests revealed leukocytosis, elevated C-reactive protein, and respiratory alkalosis." (PMID 39003491, 2024). "Over the following three days, the patient remained afebrile but had signs of a persistent leukocytosis and a rising C-reactive protein (CRP) level; due to this, her antibiotic regimen was changed with IV ciprofloxacin being replaced by IV ceftriaxone in combination with continued IV metronidazole." (PMID 39429332, 2024). "Laboratory tests showed elevated C-reactive protein (CRP) of 173 mg/L, a leukocytosis of 22.3/nL (neutrophils: 20.5/nL), and a plasma sodium of 118 mmol/L (osmolality: 248 mOsmol/kg), with concurrent acute renal failure (plasma creatinine: 202 μmol/L, plasma urea: 9.3 mmol/L)." (PMID 37856066, 2024). "Several poor prognostic factors, such as poor performance status, older age, number of metastatic organs, high serum lactate dehydrogenase (LDH) level, high serum CRP level, low serum albumin level, leukocytosis, high NLR, and visceral metastasis, were commonly mentioned in previous studies." (PMID 35781808, 2023). "Initial serum biomarkers of leukocytosis, platelet count, and CRP were similar." (PMID 36609359, 2023). "Blood tests revealed leukocytosis with neutrophilia and high C-reactive protein (CRP) levels." (PMID 36821021, 2023). "Increasing CRP levels and blood profiles showed a severe leukocytosis inflammatory pattern." (PMID 37009523, 2023). "Specifically in G1, the mean value of leukocytosis was 17 × 103/mm3, the mean value of neutrophilia was 78.1% and the mean value of CRP was 12.9 mg/dL; while in G2, the mean value of leukocytosis was 17 × 103/mm3, the mean value of neutrophilia was 79.5% and the mean value of CRP was 14 mg/dL." (PMID 37926703, 2023). "In male infants, infants aged < 1 month, infants that appeared to be well, Jews, and infants with leukocytosis > 15 × 109/L or a CRP > 2 mg/dL, the presence of respiratory symptoms reduced the risk of SBIs (p = 0.005, p = 0.011, p = 0.014, p = 0.003, and p < 0.001, respectively)." (PMID 37510751, 2023). "In the univariate and multivariate analyses of risk factors for SBIs, the male gender, an age < 1 months, leukocytosis, an elevated CRP, and a lack of respiratory symptoms increased the risk of SBIs." (PMID 37510751, 2023). "Clinical presentation was usually subacute with low-grade fever, leukocytosis, and CRP elevation." (PMID 37508277, 2023). "Leukocytosis and increased CRP can predict the occurrence of aseptic meningitis in these patients." (PMID 37349740, 2023).